INS (insulin)
Diseases named in the same sentence as INS in open-access papers (continued):
Sharing a sentence is not in itself a finding about the gene and the disease.
diabetes (continued). "Additionally, since hypertension, diabetes, and dyslipidemia are routinely treated with drugs or self‐injected insulin prescribed by medical doctors, instead of with over‐the‐counter drugs, it was possible to obtain highly accurate information on actual medication rates." (PMID 32710699, 2020). "Several pathways that trigger neurodegenerative diseases in the brain, such as impaired insulin signaling, inflammation, accumulations of advanced glycation end products (AGEs), and oxidative stress, could also trigger retinal neuropathy of type 2 diabetes mellitus patients." (PMID 32190700, 2020). "The chr8p23.1 variant rs4841132, associated with an insulin-resistant diabetes risk phenotype, lies in the second exon of a long non-coding RNA (lncRNA) gene, LOC157273, located 175 kilobases from PPP1R3B, which encodes a key protein regulating insulin-mediated hepatic glycogen storage in humans." (PMID 32754192, 2020). "Thus, the recognition of insulin secretion modulators, maintenance of function dynamics, growth, survival, and β cell activity will be an important step on the long road to our ultimate goal of glycemic control and homeostasis in diabetes." (PMID 33153226, 2020). "OLETF is a non-insulin–dependent DM model close to human type 2 diabetes model that was developed by inbreeding." (PMID 32699151, 2020). "Diabetes mellitus (DM) is a group of metabolic diseases characterized by hyperglycemia resulting from a defect in insulin secretion and/or action." (PMID 32466561, 2020). "Researchers have postulated that diabetes could be a novel mechanism of neurodegeneration wherein the classical AD pathophysiology can be explained from the perspective of unregulated insulin/IGF (insulin‐like growth factor) signaling and improper glucose metabolism." (PMID 32170854, 2020). "Three studies with insulin initiation as a marker of diabetes progression reported aHRs ranged from 1.22 to 2.23 per 1% increase in baseline HbA1c.46, 48, 52 The fourth prospective study assessed predictors of beta‐cell stress, using proinsulin/insulin (PI/I) ratio as a surrogate measure." (PMID 32318630, 2020). "Comparative examination of the active principles of quercetin and coumarin with sitagliptin, a synthetic DPP-IV-based antidiabetic drug, revealed that quercetin and coumarin might utilize in the treatment of diabetes through DPP-IV inhibition or insulin stimulation." (PMID 32023875, 2020). "Very strong effects of STZ-induced diabetes on cytokine levels indicate that the changes may be too profound to be relevant to those observed in diabetic patients, since patients with T1D are treated with insulin." (PMID 33204216, 2020). "Furthermore, increasing prices may delay initiation of diabetes medications other than insulin or metformin." (PMID 33246453, 2020). "In general, there are two types of diabetes: type 1 diabetes is caused by the lack of insulin production owing to the destruction of insulin-producing pancreatic beta cells, whereas type 2 diabetes results from insulin resistance in the muscles, liver, and adipose tissues." (PMID 32397640, 2020). "FoxO signaling pathway: FoxO proteins, which could regulate insulin signaling, gluconeogenesis, insulin resistance, immune cell migration, and cell senescence, have become new clinical entities to treat metabolic disorders and diabetes mellitus." (PMID 33292335, 2020). "Diabetes is caused by either not enough insulin, which is a hormone produced by pancreas that regulates blood glucose metabolized for energy, or insulin‐resistant cells which cannot respond properly to insulin." (PMID 31691506, 2020). "Our results showed that treatment of type 2 diabetes mellitus patients with 1-g metformin twice daily in combination with insulin significantly increases the initial systolic and diastolic blood pressure drop 30 s after standing when compared with placebo in combination with insulin treatment." (PMID 32979921, 2020).
diabetes (continued). "Furthermore, the upset of both the glucose and lipid metabolism of endothelial cells has been hypothesized as creating the conditions that favour the metabolic syndrome and decrease in insulin efficiency found in diabetes." (PMID 32168836, 2020). "Diabetes (diabetes mellitus, DM) comprises a group of metabolic disorders characterized by hyperglycemia resulting from disorders in insulin secretion or action." (PMID 33066307, 2020). "Thus, it is worth investigating whether butyric acid controls the activity of Ffar2 or HDAC to regulate the insulin secretion in different types of diabetes." (PMID 32404878, 2020). "Diabetes mellitus (DM) is one of the most important public health challenges worldwide, of which type 1 diabetes mellitus (T1DM) is characterized by hyperglycemia caused by autoimmune destruction of pancreatic β-cells, the main site of insulin production and secretion." (PMID 32489555, 2020). "Moreover, systemic inhibition of VEGF-A or VEGF-B signaling by injecting neutralizing monoclonal antibodies have also shown remarkable effects in improving insulin sensitivity in the muscle, adipose tissue, and the liver of high-fat diet-induced mouse models of obesity and diabetes." (PMID 33107824, 2020). "In rodents and humans, MetR improves glucose homeostasis and insulin sensitivity and prevents weight gain; therefore, the amount of Met intake may be related to the impairment of glucose and lipid metabolism, in addition to diabetes-induced renal injury." (PMID 32145700, 2020). "Diabetes mellitus (DM) is an alarming metabolic disease in which insulin secreting β-cells are damaged to various extent." (PMID 32064260, 2020). "Altered sensitivity to insulin has been found in disease conditions such as obesity, insulin resistance, diabetes mellitus (DM), and cancer." (PMID 32414222, 2020). "Diabetes mellitus (DM) is a group of metabolic diseases that is characterized by hyperglycaemia resulting from defects in insulin secretion from the beta cells, insulin's action, or a combination of both." (PMID 33133220, 2020). "However, impairment of glucose-stimulated insulin secretion as a result of oxidative stress and inflammation can result in β-cell dysfunction and insulin resistance, subsequently leading to the pathogenesis of type 2 diabetes mellitus (T2DM)." (PMID 32599958, 2020). "Diabetes mellitus (DM) is a serious lifelong condition, which occurs when the pancreas does not produce enough insulin, or when the body cannot effectively use the insulin it produces leading to hyperglycemia." (PMID 31752802, 2019). "Diabetes mellitus (DM) is a disease of disturbed metabolism wherein aberrant insulin secretion and/or action leads to hyperglycemia." (PMID 32038127, 2019). "Interestingly, recent literature confirms that insulin resistance is a common background for both obesity and diabetes mellitus type 2 and that insulin is a key factor also in the uptake of glucose by ovarian tissues during the menstrual cycle of some rodent, primate and ruminant species." (PMID 31307376, 2019). "Helicobacter pylori (H. pylori) may be involved in diabetes and other insulin-related processes." (PMID 31409000, 2019). "In terms of pathology, diabetes is the result of chronic high blood sugar stemming from either low insulin production, as observed in type 1 diabetes; or to a severe reduction in the response of insulin receptors (IR) to insulin, as observed in type 2 diabetes." (PMID 30766472, 2019). "However, it remains unknown whether FGF21 is involved in insulin expression and secretion that are dysregulated in type 2 diabetes mellitus (T2DM)." (PMID 30461198, 2019). "STZ-induced diabetes in mice or rat is associated with thermal hyperalgesia in early phases and with thermal hypoalgesia in late stages of diabetes in the absence of insulin therapy." (PMID 31013625, 2019). "Furthermore, it is known that FFA may enhance basal and glucose-stimulated insulin secretion among individuals including those with diabetes." (PMID 31499737, 2019).
diabetes (continued). "Our results indicate towards a critical role for miR-449a and its target, Jag1 in regulating Notch signalling and insulin signalling in the skeletal muscle and imply that targeting this axis might hold therapeutic potential for impaired skeletal muscle metabolism during diabetes." (PMID 31345231, 2019). "It is furthermore a widely used (Aptekam, Armstrong, Coradini, & Rand, 2014), but imperfect method to adjust insulin doses in cats with diabetes mellitus (DM, Roomp & Rand, 2013)." (PMID 30375076, 2019). "Diabetes mellitus (DM) is a metabolic disturbance resulting from constant hyperglycemia due to modifications in the production and/or the action of insulin." (PMID 31612148, 2019). "Diabetes Mellitus (DM) is a complex metabolic disease characterized by hyperglycemia resulting from impairments in insulin secretion, insulin action, or both." (PMID 31013914, 2019). "Diabetes mellitus (DM) is a metabolic disorder characterized by hyperglycemia, which arises from insufficient insulin secretion, insulin resistance, or augmented glucagon production." (PMID 31847392, 2019). "Some of the obtained canonical pathways were related to insulin and glucose, such as opioid signalling pathway, G-protein coupled receptor, glycine betaine degradation, nitric oxide signalling in the cardiovascular system, gustation pathway or type 2 diabetes mellitus." (PMID 31208038, 2019). "Diabetes or diabetes mellitus is referred to as a heterogeneous group of metabolic disorders characterized by chronic hyperglycemia and carbohydrate, fat and protein metabolism disorders that result from a defect in the secretion of insulin, or impairment in its function, or both." (PMID 30884193, 2019). "Advanced maternal age, family history of diabetes, pre-gestational obesity, increased level of HbA1c, history of gestational diabetes mellitus (GDM), and poor pregnancy consequences are considered risk factors for antenatal insulin requirement in women with GDM." (PMID 31656196, 2019). "Furthermore, it should be noted that in individuals with diabetes high intensity interval training may improve insulin-stimulated glucose uptake at the tissue and organ level as previously suggested." (PMID 30387015, 2019). "Furthermore, insulin values were significantly higher in the diabetes group than the control group." (PMID 31372137, 2019). "Type 1 diabetes mellitus (T1DM), known as a kind of autoimmune diabetes, is a multifactorial disease by the deficiency of secreting insulin in islet β cells to influence the normal organism metabolism, ultimately leading to elevated blood glucose levels and a severe decline in insulin secretion." (PMID 30606242, 2019). "Islet transplantation can reduce the dependence of patients with exogenous insulin, and effectively control blood sugar levels and reduce the occurrence of complications by increasing the number of islet cells with endocrine function to treat or even cure diabetes." (PMID 32038250, 2019). "Its findings could enable the more rational design of inhibitors in the hormone aggregation process, which is crucial not only from the point of view of developing new drugs for the treatment of diabetes, but also of designing additives for stabilizing insulin preparations." (PMID 31018524, 2019). "A diagnosis of diabetes was not an inclusion criterion due to the limitations of using diagnosis codes for identifying at risk patients and because patients undergoing glucose monitoring with insulin orders were considered a more relevant population." (PMID 31775749, 2019). "One may speculate that metformin exerts insulin secretagogue ability only in subgroup of metabolically compromised individuals, however, to prove this additional research in patients with metabolic syndrome and diabetes is needed." (PMID 31703101, 2019).
diabetes (continued). "Indeed, a number of studies have shown that autoantigen-specific Treg cells are able to prevent the development of T1D as well as reverse the established diabetes in rodent models: Insulin B chain 9–23 peptide is known to induce Treg cells that produce TGF-beta in NOD mice to prevent T1D." (PMID 31781669, 2019). "The pre-diabetes stage can sustain for many years attributing to β cell compensation (i.e., increased β cell mass and workload) till β cell compensation failure, which leads to the second stage featured by β cell death, decreased insulin levels in the circulation and prolonged hyperglycemia." (PMID 31721726, 2019). "Diabetes mellitus (DM) is one of the most common endocrine disorders resulting from adiminished insulin secretion or insulin action or both." (PMID 31435617, 2019). "Other studies, however, have shown AT2R activation reduces adiposity, improves glucose uptake and insulin sensitivity, and increases nitric oxide-mediated microvascular perfusion to enhance insulin delivery and action in skeletal muscle of male rodent models with diabetes and metabolic syndrome." (PMID 31262355, 2019). "Similarly, general recommendations for patients with DM2, published by the American Diabetes Association (ADA) and the European Association for the Study of Diabetes (EASD), include insulin and insulin analogs as treatment options in dual and triple anti-hyperglycemic therapy." (PMID 31798448, 2019). "Diabetes mellitus is a metabolic disorder caused by a lack of insulin." (PMID 31316568, 2019). "Nearly 30–40% and 15–20% of patients with type 1 and type 2 diabetes on insulin therapy, respectively, suffer from severe hypoglycemia with an incidence of 1.0–1.7 episodes per patient per year, because the physiological counterregulatory response to hypoglycemia is impaired in diabetes." (PMID 30503832, 2019). "Furthermore, our study findings confirm those of other studies that the use of mobile technologies such as smartphone applications, insulin pump and continuous glucose monitor could enhance diabetes self-management in patients." (PMID 31166971, 2019). "Although metabolic syndrome may independently coexist with monogenic diabetes, MODY mutation carriers seem to be characterized by relatively more pronounced insulin secretion defect, hence good diagnostic performance of combination of BMI with fasting serum C-peptide." (PMID 30778899, 2019). "The first type is known as insulin dependent diabetes mellitus (IDDM) caused by a genetic factor such as the destruction of pancreatic β-cells which produce insulin and type 2 is non-insulin dependent diabetes (NIDDM) caused by a wrong lifestyle especially on diet." (PMID 31316568, 2019). "Baldwa, and Khanna observed evidence for the insulinomimetic properties of p-insulin by demonstrating that subcutaneous administration of p-insulin; a small, insulin-like polypeptide isolated from M. charantia; reduced blood glucose in patients with diabetes in a clinical setting." (PMID 31516543, 2019). "Therefore, type 2 diabetic patients who use both oral hypoglycemic agents and insulin injections may have more severe symptoms of diabetes." (PMID 31726788, 2019). "Adherence exhibits significant beneficial effects on fatigue and social interaction for insulin-using patients with diabetes, emotional well-being for patients with myocardial infarction, and glycated hemoglobin (HbA1c) for patients with myocardial infarction and diabetes." (PMID 31094324, 2019). "Diabetes mellitus (DM) is characterized by chronic hyperglycemia resulting from the defects in insulin secretion, insulin action, or both." (PMID 30926860, 2019). "Indeed, epidemiological studies have confirmed the link between arsenic exposure and diabetes, with arsenic being correlated specifically with indices of β-cell dysfunction or decreased insulin secretion, more powerfully than with indices of insulin resistance." (PMID 30881345, 2019).
diabetes (continued). "Hence our analysis provides insights on possible mechanisms by which differential tissue insulin resistance could be responsible for diabetes, obesity and cancer, simultaneously." (PMID 31653897, 2019). "Furthermore, they observed that fasting insulin, a risk factor for type-2 diabetes mellitus, decreased with greater fiber intake, independent of energy and carbohydrate intake." (PMID 29143934, 2019). "This might be due to patients who were prescribed with insulin could have more severe diabetes and diabetes of a longer duration.This was largely contributed by the fact that -cell function worsened as the duration of diabetes increased from the time of diagnosis through follow up." (PMID 31464602, 2019). "Diabetes mellitus (DM) is a chronic metabolic disorder that occurs when the body’s response to insulin is impaired because of the incapacity of pancreas to produce enough insulin or the body cannot effectively use the insulin produced." (PMID 31048925, 2019). "Furthermore, the consumption of ginger could reduce the levels of fasting plasma glucose, glycated hemoglobin A (HbA1C), insulin, TG, and TC in patients with type 2 diabetes mellitus (DM2)." (PMID 31151279, 2019). "On the other hand, metabolism of glucose and lipids in skeletal muscles during the resting state and insulin action in insulin-resistant individuals are improved by both aerobic and resistance exercises in skeletal muscle leading to decreased conversion rates to overt diabetes." (PMID 31226872, 2019). "Thus, the influence of dietary polyphenols on blood glucose at different levels may also help control and prevent diabetes complication via a decrease of hyperglycemia and an improvement of acute insulin secretion and insulin sensitivity." (PMID 31083443, 2019). "T2DM is a disease that affects 90–95% of all adult diabetes patients and is caused by a lack of insulin secretion from the β-cells of the pancreas or by insulin resistance that arises from the inability of insulin to act normally in regulating nutrient metabolism in peripheral tissues." (PMID 31339947, 2019). "Similar to type 2 diabetes mellitus (DM), decreased insulin secretion and increased insulin resistance are important to the pathophysiologic mechanism behind NODAT." (PMID 31252561, 2019). "Impairment in insulin production or improper use of insulin, or both, lead to changes in blood glucose levels resulting in the most common metabolic disorder known as diabetes mellitus (DM)." (PMID 31108878, 2019). "Being born from a mother with pre-existing diabetes mellitus (DM) or gestational DM (GDM) is another risk factor for obesity and impaired insulin sensitivity, even in offspring with normal birth weight." (PMID 31214120, 2019). "The cascade linking hyperglycemia or diabetes to a reduction in cognitive function probably involves aging and genetic factors, as well as factors such as arteriosclerosis, microvascular disease, insufficient insulin action, oxidative stress, and glucotoxicity." (PMID 31014232, 2019). "RPG represents an FDA-approved drug for the treatment of type 2 diabetes mellitus (DM), that rapidly lowers blood glucose levels by stimulating the insulin release from the pancreas through inhibition of the KATP channel activity." (PMID 31861249, 2019). "Consequently, some diabetes patients may take a DPP4 inhibitor such as Sitagliptin to increase insulin secretion for diabetes therapy and ameliorate the therapeutic effect of GLP-1." (PMID 31652794, 2019). "Despite having sufficient insulin, individual may have higher FBG value which is mainly due to insulin resistance that is the commonest cause of impaired fasting glucose tolerance and diabetes mellitus." (PMID 31080251, 2019).